INS (insulin)
Diseases named in the same sentence as INS in open-access papers (continued):
Sharing a sentence is not in itself a finding about the gene and the disease.
Obesity (continued). "This study suggests that DNAsome-based siRNA delivery systems hold promise for improving insulin sensitivity and addressing IR associated with obesity and metabolic syndrome." (PMID 39906612, 2025). "In metabolic diseases, the gut microbiota regulates energy balance and lipid/glucose metabolism, modulates insulin sensitivity, and is closely associated with obesity, T2D, and MASLD." (PMID 40332366, 2025). "The mechanisms underlying obesity-related hypertension include insulin- and leptin-mediated activation of the sympathetic nervous system, which in turn stimulates the renin–angiotensin–aldosterone system (RAAS) and promotes renal sodium retention." (PMID 41150735, 2025). "It is likely that a reduction in insulin levels contributes to the anti-cancer effects of insulin, especially on cancer types that have been linked with obesity, metabolic syndrome, and hyperinsulinemia, including gastrointestinal and breast cancers." (PMID 39941833, 2025). "Fat accumulation in the liver (steatosis) preceding T2D is associated with obesity and reduced hepatic insulin sensitivity, leading to fasting hyperglycemia." (PMID 40362446, 2025). "CAG:471 on the worsening of insulin sensitivity, and demonstrated an positive association with adverse metabolic profiles, such as obesity and elevated blood pressure." (PMID 40413611, 2025). "Comprehensive endocrine evaluation, including pituitary axis profiling, dynamic growth hormone testing, and assessments of insulin and leptin resistance, excluded secondary causes of obesity and reinforced the likelihood of a monogenic etiology." (PMID 40428329, 2025). "In turn, the downregulation of miR-184 has been associated with obesity-related inflammation, insulin secretion, and resistance through aberrant PKCβ and AKT2 signalling." (PMID 41356094, 2025). "-Associated with BMI in postmenopausal women (n=267).-Associated with lower-body obesity in women with obesity.-In postmenopausal women, E1 is inversely correlated with adiponectin and insulin sensitivity (n=101)." (PMID 41180177, 2025). "Maternal obesity causes metabolic issues in offspring, including excess insulin levels, leading to heightened sensory innervation and airway sensitivity, possibly influencing asthma inheritance." (PMID 39782687, 2025). "The accumulation of macrophages and their pro-inflammatory polarization are hallmarks of the obesity-associated AT inflammation, in turn resulting in the development of systematic inflammation, dysfunctional insulin action and metabolic disorders." (PMID 40368890, 2025). "The absence of a cephalic phase insulin response has been linked to impaired insulin secretion and an elevated risk of obesity." (PMID 40291991, 2025). "Age-related decline in insulin sensitivity, compounded by higher rates of obesity and metabolic syndrome, contribute to this association." (PMID 41552136, 2025). "MASLD is prevalent among adults and increasingly recognized in younger populations, emphasizing the need for age-specific reference values for fasting glucose-insulin metabolism to enhance risk stratification, especially in children with obesity." (PMID 40672815, 2025). "A high-fat diet (HFD) is one of the direct causes of obesity, as it increases calorie intake and impairs insulin sensitivity in the liver." (PMID 40867585, 2025). "PCSK1 gene mutation has been linked to various endocrine disorders, including KS, metabolic disturbances, increased appetite, insulin dysregulation, and potential predispositions to obesity." (PMID 40724652, 2025). "Chemerin is closely associated with obesity, inflammation, and vascular dysfunction, acting as a key regulator of glucose and lipid metabolism through the modulation of insulin sensitivity, lipolysis, and adipocyte differentiation." (PMID 41334336, 2025).
Obesity (continued). "Previous studies have found that miR-802 is increased in the pancreatic islets of mouse models with obesity and overexpression of miR-802 in mice causes impaired insulin transcription and secretion." (PMID 41002956, 2025). "This is consistent with studies showing that modest weight loss and lifestyle modifications improve insulin dynamics in youth with obesity." (PMID 40978311, 2025). "Increasing evidence indicates that persistent inflammation elicited by obesity results in the loss of insulin pathway and internal balance control mechanisms, serving as the mechanism linking obesity to primary CRC." (PMID 41164182, 2025). "At the same time, while prior studies have focused on common obesity-associated SNPs or large CNVs, this study specifically investigated smaller CNVs in the genes involved in leptin signalling and insulin resistance." (PMID 40429924, 2025). "Deficiency disrupts insulin sensitivity and enhances inflammatory signaling, exacerbating metabolic derangements typical of obesity." (PMID 41305652, 2025). "Our findings align with previous research indicating the beneficial role of PUFAs in modulating obesity risk through mechanisms such as improved lipid metabolism, enhanced insulin sensitivity, and anti-inflammatory effects." (PMID 40944253, 2025). "Increased insulin was associated with higher risk of developing GDM from up to 10 weeks prior to diagnostic testing in women living with obesity, however the certainty of evidence was very low." (PMID 41019841, 2025). "Genetic studies have identified key obesity-associated genes involved in appetite regulation, insulin secretion, adipogenesis, lipid metabolism, and pathways linked to obesity-related metabolic dysfunction." (PMID 40428320, 2025). "TNF-α is one of the key mediators of obesity-associated inflammation and can inhibit insulin signaling by activating the JNK/NF-κB pathways, impairing insulin receptor phosphorylation, and contributing to hepatic lipotoxicity." (PMID 40862455, 2025). "Obesity can cause disturbances in lipid and carbohydrate metabolism, alterations in insulin signaling, pathological enlargement of visceral white adipose tissue (vWAT) and inflammation." (PMID 41301714, 2025). "The ZDF rats, as a genetic model of obesity, exhibit hyperleptinemia and associated leptin resistance, which results in a deterioration in insulin sensitivity." (PMID 39576482, 2025). "Elevated BCAA levels have been associated with obesity and insulin-resistant conditions due to disruptions in protein anabolism and impaired insulin signaling." (PMID 39796608, 2025). "Our research specifically examined how obesity, elevated insulin levels, and vitamin D deficiency contribute to androgen excess, further exacerbating the clinical manifestations of the syndrome." (PMID 40868057, 2025). "IL6 JAK-STAT signaling has been reported to impair the insulin-degrading enzyme, a protein found to be associated with obesity and T2D45." (PMID 39670387, 2025). "The low exposure to insulin growth factor, lipid levels, and insulin resistance have all been proposed as pathways to explain the association between cancer and obesity." (PMID 40002302, 2025). "Central insulin and leptin resistance, hypothalamic inflammation, and impaired brainstem autonomic control are implicated in the pathogenesis of obesity and T2DM." (PMID 41409607, 2025). "In genetically modified rat models, such as the leptin-receptor-deficient obese Zucker fa/fa rats, obesity, hyperlipidemia, and impaired insulin metabolism develop compared to the lean Zucker rats." (PMID 39858515, 2025). "This chronic and progressive disease develops due to the body’s inability to effectively utilize insulin or insufficient insulin production, and its rising incidence is inextricably linked to the worldwide obesity epidemic." (PMID 40507022, 2025).
Obesity (continued). "This age‐dependent shift toward insulin therapy likely reflects sarcopenic obesity—a hallmark of aging characterized by muscle loss and visceral fat accumulation." (PMID 41383356, 2025). "Studies link obesity to a higher risk of various cancers and poorer treatment outcomes, driven by pro-inflammatory signaling, hormonal disruptions, and insulin resistance that create a tumor-friendly environment." (PMID 41312241, 2025). "This methylation site was also linked to numerous obesity-related traits, specifically those that measure body fat composition and insulin sensitivity." (PMID 40355419, 2025). "Insulin therapy is a novel treatment modality for AD, and there is evidence that diet-induced obesity and insulin dysregulation are closely linked to a range of pathological changes such as Aβ amyloid deposition and Tau protein aggregation in AD." (PMID 39944627, 2025). "Its elevated activity in obesity enhances the formation of mitochondria-associated endoplasmic reticulum membranes while suppressing insulin signaling." (PMID 40652248, 2025). "The mitogen-activated protein kinase (MAPK) insulin pathway underlies numerous obesity-related malignancies that regulate cell growth and mitosis." (PMID 40141412, 2025). "In this unique twin study, obesity was associated with increased insulin‐stimulated glucose uptake in the caudate and parietal cortex and with elevated resting‐state brain activity in regions of the default mode network." (PMID 40926735, 2025). "Research has shown that the rise in T2DM prevalence is strongly associated with the worldwide increase in obesity since it affects both insulin and beta cell function." (PMID 41007838, 2025). "Key search terms included: “Magnesium” OR “Serum Magnesium” OR “Magnesium Deficiency” AND “Insulin Resistance” OR “HOMA-IR” OR “Insulin Sensitivity” AND “Overweight” OR “Obese” OR “Obesity” AND “Children” OR “Pediatric” OR “Adolescents”." (PMID 40895688, 2025). "In conclusion, although differing in molecular mechanisms, EPO exerts anti-inflammatory and metabolic actions in key insulin-sensitive tissues, positioning it as a compelling target in obesity-associated metabolic disorders." (PMID 40697664, 2025). "By establishing the causal sequence between dopaminergic deficiency, altered insulin signaling, and metabolic vulnerability, this study provides a framework for understanding the neurobiological basis of some forms of obesity." (PMID 41279682, 2025). "T2D development is closely associated with obesity-induced inflammation, which impairs insulin sensitivity by damaging pancreatic beta cells, ultimately leading to insulin resistance." (PMID 41277875, 2025). "In a mouse model of high-fat diet-induced obesity, deletion of Slc16a1 causes lactate accumulation and aggravates systemic insulin resistance, macrophage recruitment, and cytokine expression." (PMID 39198360, 2025). "Peripheral IR, which is associated with obesity, leads to an impaired ability of insulin to regulate glucose and lipid metabolism, resulting in elevated levels of FFAs released from adipose tissue." (PMID 40869259, 2025). "It stimulated the release of miRNAs, such as miR-103-3p and let-7f-5p, which were associated with obesity and disrupted insulin signaling in the liver." (PMID 40001534, 2025). "The pathophysiology associated with obesity shares similarities with that observed in normal aging, encompassing alterations in metabolic regulation, insulin resistance, inflammation, and compromised immune function." (PMID 40074999, 2025). "mTORC1 signaling mediates inhibition of the PI3K/AKT pathway and is activated by increased amino acids, insulin, and pro-inflammatory cytokines caused by overnutrition in obesity." (PMID 40076851, 2025). "Statin use was significantly associated with baseline LDL-C, total cholesterol, insulin therapy, and obesity." (PMID 40785972, 2025).
Obesity (continued). "Elevated BMI, a key component of the BAN score, is a hallmark of obesity, which is closely linked to persistent subclinical inflammation and diminished insulin sensitivity, both central features of metabolic syndrome." (PMID 41008514, 2025). "In obesity, insulin-resistant adipose tissue is associated with defective systemic glucose handling." (PMID 40650249, 2025). "While insulin resistance associated with obesity plays a key role in the early stage of T2D development, insufficient insulin secretion due to decreased beta cell function (BCF) is the decisive factor in the final stage of T2D development." (PMID 39921368, 2025). "Given that adipokines such as adiponectin and leptin are secreted by adipose tissue in obesity, which leads to inflammation, weight loss following a yogic diet and lifestyle changes lessens inflammation in adipose tissue and increases insulin sensitivity." (PMID 40216734, 2025). "As expected from its roles, FFAR4-deficiency increased obesity upon high-fat-diet feeding and resulted in IR and hepatic fat accumulation with impaired insulin signaling activity and increased inflammation in adipose tissues." (PMID 40427589, 2025). "FXR activation in the liver and intestines inhibits hepatic lipogenesis, enhances insulin sensitivity, and increases energy expenditure, collectively reducing obesity risk." (PMID 40183584, 2025). "By modulating these pathways, anthocyanins restrict pro-inflammatory cytokine biosynthesis and restore insulin sensitivity, which plays a significant role in combating metabolic dysfunction caused by obesity." (PMID 40218884, 2025). "Afternoon exercise training has gained recent attention since it has been linked to better glucose metabolism and insulin sensitivity among people with obesity." (PMID 39421964, 2025). "Analogously to 5-AMQ, in C57BL/6 mice with high-fat diet-induced obesity, 6MeONa treatment caused a reduction in body weight, improved insulin sensitivity and normalized glucose tolerance to the level of lean control mice." (PMID 41301471, 2025). "Postbiotic administration has also been linked to improved insulin sensitivity and reduced body weight, emphasizing their role in the prevention and treatment of obesity-related metabolic disorders." (PMID 39974837, 2025). "These hormonal shifts work synergistically to promote weight loss, enhance insulin sensitivity, and resolve obesity-related complications." (PMID 41155711, 2025). "Previous studies typically and superficially characterize beige fat as beneficial, associating its presence with insulin sensitivity and protection against obesity-associated metabolic dysfunction." (PMID 41206127, 2025). "The overexpression of microRNA-143 caused by obesity inhibits insulin-stimulated AKT activation and disrupts glucose metabolism, and microRNA-143 is a novel regulator of T2DM." (PMID 39912972, 2025). "In this context, obesity is associated with a lower insulin sensitivity, and higher homeostasis model assessment of insulin resistance scores—HOMA-IR and HOMA2-IR." (PMID 40257685, 2025). "IGFBP-1 has a long-established inverse association with obesity, which is likely mediated by changes to insulin levels." (PMID 40987470, 2025). "Genome‐wide association studies (GWAS) have identified numerous genetic variants associated with obesity, involving pathways related to food intake, energy expenditure, adipocyte maturation, and insulin signaling." (PMID 40551726, 2025). "In humans, obesity is associated with metabolic impairments in skeletal muscle, including diminished insulin-induced glucose uptake, reduced oxidative metabolism, and increased lactate production." (PMID 40522819, 2025). "At baseline, obesity was associated with increased insulin‐stimulated BGU and resting state brain activity, independent of genetics." (PMID 40926735, 2025). "In other species, an association exists among obesity, insulin dysregulation, and increased oxidative stress." (PMID 40048369, 2025).
Obesity (continued). "Consumption of healthy grains was associated with lower obesity rates and lower fasting insulin levels." (PMID 40871702, 2025). "Obesity, hyperinsulinemia, and changes in insulin clearance in humans are strongly associated with the accumulation of lipid in the liver (MASLD), so we also investigated lipid accumulation in HI and control horses." (PMID 40476757, 2025). "Sustained bodyweight reduction among people with obesity is associated with decreased cardiometabolic risk, as well as improved insulin sensitivity, pancreatic β‐cell function and hepatic triglycerides." (PMID 40555920, 2025). "Protection of MestpKO female mice from dietary obesity was associated with improved glucose tolerance and insulin sensitivity." (PMID 41234240, 2025). "Polyphenols have been shown to improve the inflammatory state associated with obesity and enhance insulin sensitivity." (PMID 41300428, 2025). "Obesity in horses can also contribute to insulin dysregulation and therefore increase the risk of performance-limiting laminitis." (PMID 40362130, 2025). "The risk for cancer was not related to the patient’s underlying condition (T1D, T2D, overweight/obesity) or influenced by the control (placebo, insulin, or another antihyperglycemic drug)." (PMID 41178720, 2025). "Another study proved that LEAP2 is associated with increased insulin secretion in adults with obesity and overweight." (PMID 39796232, 2025). "For instance, obesity and hyperglycemia are associated with elevated levels of insulin and insulin-like growth factors, which can promote tumor initiation and progression by stimulating cellular proliferation and inhibiting apoptosis." (PMID 40747172, 2025). "Variability in salivary amylase activity (SAA), driven largely by copy number variation of AMY1, has been associated with postprandial glycemic responses, insulin secretion dynamics, and susceptibility to obesity." (PMID 40806495, 2025). "Experimental restoration of Hem2atm expression resulted in a substantial reduction in obesity-associated inflammatory processes and improved insulin sensitivity." (PMID 40869388, 2025). "In particular, fetal macrosomia—often linked to maternal diabetes or obesity—results in chronic exposure to elevated glucose and insulin levels, which can promote myocardial hypertrophy and altered cardiac remodeling." (PMID 40648876, 2025). "Obesity and a sedentary lifestyle are major contributors to the loss of insulin sensitivity and reduced glucose uptake in peripheral tissues, particularly skeletal muscle, liver, and adipose tissue." (PMID 40862756, 2025). "In obesity models, administering an AhR-linked signal that boosts IL-22 improved gut barrier function and reduced weight gain and insulin resistance." (PMID 40871736, 2025). "In fact, it has been observed that men with obesity receiving faecal transplants from lean donors had an increase in insulin sensitivity associated with an increase in butyrate producing bacteria in the gut 6 weeks post transplantation." (PMID 40051343, 2025). "ST3GAL5-deficient model mice exhibited improved insulin sensitivity and reduced high-fat diet-induced obesity." (PMID 41301440, 2025). "Multiple studies have demonstrated that, beyond excessive calorie consumption, the elevated added sugar content in sweetened drinks can induce high glycemic load and exaggerated insulin response, consequently elevating obesity risk." (PMID 40944145, 2025). "DNAm changes affecting CpG sites in genes involved with lipid metabolism and insulin sensitivity pathways were common in all three tissue types, indicating that PA does have an epigenetic effect on pathways associated with obesity." (PMID 40283858, 2025). "Beyond excessive body weight, obesity is linked to alterations in sex hormone metabolism, insulin and insulin-like growth factor (IGF) signaling, adipokines, and inflammatory pathways." (PMID 40427123, 2025).